CFAP20 (cilia and flagella associated protein 20)
Description:
Cilium- and flagellum-specific protein that plays a role in axonemal structure organization and motility. Microtubule inner protein (MIP) part of the dynein-decorated doublet microtubules (DMTs) in cilia axoneme, which is required for motile cilia beating. Involved in the regulation of the size and morphology of cilia. Required for axonemal microtubules polyglutamylation.
Synonyms: BUG22; C16orf80; GTL3; fSAP23; EVORF; RP107
Tractability: Small molecule: a structure with a bound ligand is known. PROTAC: ubiquitination databases record sites on it; its protein half-life has been measured.
Gene: Protein-coding gene on chromosome 16 (58,113,588 to 58,129,429, reverse strand). Ensembl gene ENSG00000070761.
Subcellular location: Nucleus; Cytoplasm, cytoskeleton, microtubule organizing center, centrosome, centriole; Cytoplasm, cytoskeleton, cilium basal body; Cytoplasm, cytoskeleton, cilium axoneme; Cytoplasm, cytoskeleton, flagellum axoneme
Subcellular location (Human Protein Atlas): Nucleoplasm; Principal piece; Equatorial segment
Gene Ontology:
Molecular function: protein binding; RNA binding
Biological process: cilium assembly; positive regulation of cell motility; positive regulation of feeding behavior; protein polyglutamylation; regulation of cilium beat frequency involved in ciliary motility; flagellated sperm motility
Cellular component: axonemal microtubule; centriole; ciliary basal body; cilium; extracellular exosome; nucleoplasm; nucleus; motile cilium; sperm flagellum; axonemal B tubule inner sheath; axoneme
Genetic constraint (gnomAD): Loss-of-function variants: 11 observed, 23.24 expected, observed/expected ratio (o/e) 0.47, 90% interval 0.3 to 0.78. The upper end of that interval is the gene's LOEUF score, 0.78, which puts it in group 3 of 6, group 1 being the genes least tolerant of losing a copy. Missense variants: 170 observed, 246.48 expected, observed/expected ratio (o/e) 0.69, 90% interval 0.61 to 0.78. Synonymous variants: 67 observed, 90.1 expected, observed/expected ratio (o/e) 0.74, 90% interval 0.61 to 0.91.
Homologues: Orthologues: chimpanzee CFAP20 (100% identical), macaque CFAP20 (100% identical), dog CFAP20 (99% identical), mouse Cfap20 (99% identical), pig CFAP20 (99% identical), guinea pig CFAP20 (99% identical), tropical clawed frog cfap20 (98% identical), zebrafish cfap20 (98% identical), Drosophila melanogaster Bug22 (93% identical), rabbit CFAP20 (82% identical), Caenorhabditis elegans cfap-20 (77% identical), rat Cfap20 (76% identical). Paralogues in human: CFAP20DC (25% identical).
Diseases named in the same sentence as CFAP20 in open-access papers:
CFAP20 is named in the same sentence as 19 diseases in open-access papers, as found by Europe PMC text mining. Sharing a sentence is not in itself a finding about the gene and the disease. The quoted sentences say what the papers report.
ciliopathies (3 papers, 2022 to 2024). "Finally, to determine if CFAP20 patient variants have reduced function we assessed their ability to rescue motile ciliopathy phenotypes in zebrafish." (PMID 36329026, 2022). "Together, our study demonstrates unexpected roles for CFAP20 within an unconventional ciliopathy domain or hub centered within the inner junction." (PMID 36329026, 2022). "Remarkably, CFAP20 interacts with disease-causing proteins including: (i) ARL2BP, associated with RP, (ii) TBC1D32 and FOXJ1, related with ciliopathies, and (iii) LRRK2 and DICER1, involved in retinal degeneration in animal models." (PMID 35246562, 2022). "CFAP20 is a ciliopathy candidate known to modulate motile cilia in unicellular eukaryotes." (PMID 36329026, 2022). "Here, the authors show the conserved protein CFAP20 is important for both motile and non-motile cilia and is distinct from other ciliopathy-associated domains or macromolecular complexes." (PMID 36329026, 2022). "Hence, CFAP20 functions within a structural/functional hub centered on the inner junction that is shared between motile and non-motile cilia, and is distinct from other ciliopathy-associated domains or macromolecular complexes." (PMID 36329026, 2022).
autosomal recessive retinitis pigmentosa (1 paper, 2022). Autosomal recessive retinitis pigmentosa (RP) is an autosomally recessive inherited retinal dystrophy leading to progressive loss of the photoreceptors and retinal pigment epithelium and resulting in blindness usually after several decades. "Although further studies are needed, we propose CFAP20 as a candidate gene for autosomal recessive retinitis pigmentosa." (PMID 35246562, 2022).
esophageal cancer (1 paper, 2025). A primary or metastatic malignant neoplasm involving the esophagus. "By integrating bioinformatics, experimental validation, and clinical correlation analyses, we identified six SFs (CRNKL1, SNRPB2, RBMX2, DDX46, PPWD1, and CFAP20) that are aberrantly overexpressed in esophageal cancer and tightly linked to poor prognosis." (PMID 40282339, 2025).
retinal disease (1 paper, 2022). "PPI network analysis of CFAP20 significantly contributed to our understanding of potential relationships between CFAP20 interactors and retinal disease mechanisms." (PMID 35246562, 2022).
Retinal dystrophy (1 paper, 2022). Retinal dystrophy is an abnormality of the retina associated with a hereditary process. "We describe eight individuals from four independent families with damaging biallelic variants in CFAP20 that segregate with retinal dystrophy." (PMID 36329026, 2022). "Human patients and zebrafish with CFAP20 mutations both exhibit retinal dystrophy." (PMID 36329026, 2022). "Patient data revealed that biallelic CFAP20 variants segregate with retinal dystrophy." (PMID 36329026, 2022). "Furthermore, we uncovered rare biallelic CFAP20 missense and canonical splice-site variants in 8 human patients from four unrelated families affected by inherited retinal dystrophy, a vastly heterogeneous condition often caused by non-motile cilia defects." (PMID 36329026, 2022).
tumor (2 papers, 2023 to 2025). "We explored the relationship between survival-related SFs and ploidy, and found that CRNKL1, SNRPB2, RBMX2, and CFAP20 showed significant positive correlations with tumor ploidy." (PMID 40282339, 2025).
cancer (1 paper, 2025). A tumor composed of atypical neoplastic, often pleomorphic cells that invade other tissues. "CFAP20, PPWD1, and DDX46 were positively correlated with cancer-associated fibroblasts (CAFs)." (PMID 40282339, 2025).
CFAP20 also shares sentences with these, for which no sentence is quoted: infection (2 papers); retinal degeneration (2); cyst (1); Hydrocephalus (1); hyperlipidemia (1); male infertility (1); Obesity (1); Parkinson disease (1); primary ciliary dyskinesia (1); renal disease (1); retinitis pigmentosa (1); retinoblastoma (1).